UTP11 (UTP11 small subunit processome component)
Description:
Part of the small subunit (SSU) processome, first precursor of the small eukaryotic ribosomal subunit. During the assembly of the SSU processome in the nucleolus, many ribosome biogenesis factors, an RNA chaperone and ribosomal proteins associate with the nascent pre-rRNA and work in concert to generate RNA folding, modifications, rearrangements and cleavage as well as targeted degradation of pre-ribosomal RNA by the RNA exosome. Involved in nucleolar processing of pre-18S ribosomal RNA.
Synonyms: UTP11L; CGI-94; CGI94
Tractability: Small molecule: a structure with a bound ligand is known. PROTAC: UniProt records ubiquitination sites on it; ubiquitination databases record sites on it.
Gene: Protein-coding gene on chromosome 1 (38,009,111 to 38,024,820, forward strand). Ensembl gene ENSG00000183520.
Subcellular location: Nucleus, nucleolus
Subcellular location (Human Protein Atlas): Nucleoli; Cytosol; Nucleoplasm
Pathways (Reactome):
Metabolism of RNA: Major pathway of rRNA processing in the nucleolus and cytosol; rRNA modification in the nucleus and cytosol
Gene Ontology:
Molecular function: protein binding; RNA binding
Biological process: nervous system development; positive regulation of apoptotic process; ribosomal small subunit biogenesis; maturation of SSU-rRNA; rRNA processing
Cellular component: cytoplasm; extracellular region; nucleolus; small-subunit processome; nucleoplasm
Genetic constraint (gnomAD): Loss-of-function variants: 27 observed, 34.76 expected, observed/expected ratio (o/e) 0.78, 90% interval 0.57 to 1.07. The upper end of that interval is the gene's LOEUF score, 1.07, which puts it in group 4 of 6, group 1 being the genes least tolerant of losing a copy. Missense variants: 269 observed, 303.04 expected, observed/expected ratio (o/e) 0.89, 90% interval 0.8 to 0.98. Synonymous variants: 106 observed, 106.33 expected, observed/expected ratio (o/e) 1, 90% interval 0.85 to 1.17.
Homologues: Orthologues: chimpanzee UTP11 (99% identical), macaque UTP11 (99% identical), guinea pig UTP11 (95% identical), dog UTP11 (94% identical), pig UTP11 (93% identical), mouse Utp11 (91% identical), rat Utp11 (90% identical), rabbit UTP11 (81% identical), tropical clawed frog utp11 (74% identical), zebrafish utp11 (64% identical), Drosophila melanogaster CG1789 (39% identical), Caenorhabditis elegans C16C10.2 (38% identical).
Diseases named in the same sentence as UTP11 in open-access papers:
UTP11 is named in the same sentence as 15 diseases in open-access papers, as found by Europe PMC text mining. Sharing a sentence is not in itself a finding about the gene and the disease. The quoted sentences say what the papers report.
breast carcinoma (2 papers, 2022 to 2023). "Our analysis of the prognostic significance of the three UTPs in breast cancer revealed that only UTP11 is highly associated with the poor prognosis with a p-value of 1.8E-09." (PMID 37087976, 2023). "In addition, immunohistochemistry (IHC) staining of UTP11 in 91 breast cancer specimens revealed that higher levels of UTP11 are significantly associated with higher tumor/node/metastasis (TNM) stages and worse overall survival of patients." (PMID 37087976, 2023). "Consistent with the results in breast cancer, UTP11 levels were higher in colorectal cancer tissues than in adjacent normal tissues, as determined by IHC staining." (PMID 37087976, 2023). "First, UTP11 expression was determined in breast cancer and paired normal tissues by IB and RT-qPCR analyses." (PMID 37087976, 2023). "Also, ablation of UTP11 induced G1 cell cycle arrest of both breast cancer cell lines, which was likely due to the upregulation of p21." (PMID 37087976, 2023). "Moreover, UTP11 ablation dramatically suppressed breast cancer cell migration, as determined by transwell assays." (PMID 37087976, 2023). "Moreover, univariate and multivariate analyses of overall survival of the 91 patients indicated that the increased level in UTP11 is a poor prognostic factor in breast cancers." (PMID 37087976, 2023). "Consistent with these cell-based results, depleting UTP11 suppressed breast cancer growth in vivo." (PMID 37087976, 2023). "Knockdown of UTP11 using two independent siRNAs significantly inhibited the viability and colony-formation of CAL-51 and MCF-7 breast cancer cells." (PMID 37087976, 2023). "Both the protein and mRNA levels of UTP11 were upregulated in breast cancer tissues compared with normal tissues." (PMID 37087976, 2023).
Alzheimer disease (1 paper, 2023). A progressive, neurodegenerative disease characterized by loss of function and death of nerve cells in several areas of the brain leading to loss of cognitive function such as memory and language. "It was reported that UTP11 is expressed in neurons of hippocampus, while downregulation of UTP11 may be associated with Alzheimer's disease, although the molecular basis is unclear." (PMID 37087976, 2023).
colorectal cancer (1 paper, 2023). A primary or metastatic malignant neoplasm that affects the colon or rectum. "In conclusion, our study as presented here identifies UTP11 as a new oncoprotein that acts to boost ribosome biogenesis and inhibit ferroptosis and is highly expressed and associated with poor prognoses in breast and colorectal cancers." (PMID 37087976, 2023). "Indeed, UTP11 is often overexpressed in breast and colorectal cancers, and higher levels of UTP11 are associated with worse prognoses." (PMID 37087976, 2023). "Since UTP11 is essential for the growth and survival of breast and colorectal cancer cells we investigated the clinical significance of UTP11 overexpression in these two types of cancer." (PMID 37087976, 2023). "To test this, we first examined if UTP11 is required for ribosome biogenesis in breast and colorectal cancer cells." (PMID 37087976, 2023). "Also, higher levels of UTP11 were significantly associated with higher TNM stages and worse prognoses in a cohort of 150 patients with colorectal cancer." (PMID 37087976, 2023). "Taken together, our results suggest that UTP11 could be a biomarker for poor prognoses of both breast and colorectal cancers and a potential target for future development of a new anti-cancer therapy." (PMID 37087976, 2023). "Furthermore, univariate and multivariate analyses revealed that UTP11 is a prognostic factor in colorectal cancer." (PMID 37087976, 2023). "We also assessed the clinical relevance of UTP11 levels in colorectal cancer." (PMID 37087976, 2023).
hepatocellular carcinoma (1 paper, 2024). A malignant tumor that arises from hepatocytes. "In future research, we aim to thoroughly investigate and confirm the role of UTP11 in promoting hepatocellular carcinoma by regulating stem cells at both the cellular and animal levels, enhancing our understanding of this crucial mechanism." (PMID 38233795, 2024). "We first investigated the UTP11 mRNA expression levels from TCGA database of an extensive number of tumors in comparison with adjacent normal tissues, and the data displayed that UTP11 showed high levels in most tumors compared to normal tissues, including hepatocellular carcinoma tissues." (PMID 38233795, 2024). "Several publications suggest that UTP11 may be a promising gene engaged for involvement of hepatocellular carcinoma (HCC) pathology." (PMID 38233795, 2024). "This study also did not delve deeply into the specific mechanisms through which UTP11 regulates stem cells to promote hepatocellular carcinoma growth." (PMID 38233795, 2024).
liver cancer (1 paper, 2024). An epithelial or non-epithelial malignant neoplasm that arises from the liver. "To validate the involvement of UTP11 in tumor stemness in liver cancer, we analyzed with TCGA database to detect the relationship between tumor stemness scores and mRNA levels of UTP11." (PMID 38233795, 2024). "As a further verification of the utilization of UTP11 on liver cancer, we firstly inspected the UTP11 levels in normal human liver cells (HL-7702) and HCC cell lines (Bel-7404, Huh7, HepG2, HCC-LM3) by qRT-PCR assay." (PMID 38233795, 2024). "The levels of UTP11 were remarkably enhanced in liver cancer cell lines compared to HL-7702 cells, with the highest expression levels in HepG2 and HCC-LM3 cell lines." (PMID 38233795, 2024). "Our data indicated that UTP11 levels were much higher in HCC samples compared to normal tissues; ROC curves revealed that UTP11 was able to discriminate considerably between liver cancer tissues and paraneoplastic samples, which are consistent with the previously reported literatures." (PMID 38233795, 2024). "Similarly, our ultrasound data indicated that the sizes of liver cancers in the UTP11 knocking down groups were clearly shrinking to those in the controls." (PMID 38233795, 2024). "With a view to gaining further knowledge on the mechanism of how UTP11 promotes the growth of liver cancer, we first used the CCLE database, a database containing 25 HCC cell lines, to test the functions of UTP11 involved in liver cancer cells." (PMID 38233795, 2024).
cancer (3 papers, 2022 to 2024). A tumor composed of atypical neoplastic, often pleomorphic cells that invade other tissues. "In this study, we showed that UTP11 is highly expressed and associated with poor prognoses in multiple human cancers." (PMID 37087976, 2023). "However, the role of UTP11 in cancer development and the underlying mechanism remain largely elusive." (PMID 37087976, 2023). "UTP11 is overexpressed in human cancers and associated with poor prognoses." (PMID 37087976, 2023). "Notably, several other NRF2 target genes, such as HMOX1 and NQO1, which are associated with antioxidant activity and ferroptosis, were also downregulated in UTP11-deficient cancer cells." (PMID 37087976, 2023). "Moreover, higher levels of UTP11 were associated with worse prognoses in various cancers." (PMID 37087976, 2023). "Through our analysis of TCGA database, we also found that the UTP11 gene is amplified in human cancers." (PMID 37087976, 2023). "Additionally, the protein levels of Ki67 and PCNA, the proliferating indicators of cancer, were found to be greatly reduced in the UTP11 knockdown samples." (PMID 38233795, 2024). "On the contrary, UTP11 overexpression significantly promoted the growth, colony formation, and migration of cancer cells." (PMID 37087976, 2023). "Considering SLC7A11 is critical for the uptake of cystine and synthesis of GSH, we tested if UTP11 might affect GSH levels in cancer cells." (PMID 37087976, 2023). "Conversely, UTP11 overexpression promotes cancer cell growth and migration." (PMID 37087976, 2023). "Our results also suggest that targeting UTP11 might be an attractive strategy to eliminate cancer cells by inducing nucleolar stress and ferroptosis." (PMID 37087976, 2023). "Concerning UTP11, there are limited publications on its involvement in cancer." (PMID 35625741, 2022).
cancer (continued). "Interestingly, UTP11 levels were positively correlated with the expression of both genes in cancer, suggesting that UTP11-mediated ribosome biogenesis and ferroptosis inhibition might contribute to a poor cancer prognosis." (PMID 37087976, 2023). "Ablation of UTP11 markedly repressed NRF2 expression at both mRNA and protein levels in multiple cancer cell lines." (PMID 37087976, 2023).
tumor (3 papers, 2012 to 2024). "Further, UTP11 was positively correlated with tumor stemness scores and stemness-associated proteins from TCGA database." (PMID 38233795, 2024). "The correlation of UTP11 and tumor stemness scores and stemness-associated proteins from TCGA database." (PMID 38233795, 2024). "Next, we analyzed the relevance of UTP11 expression to tumor stemness-associated proteins through heat map, which showed a positive correlation between UTP11 expression and tumor stemness-associated proteins, with the strongest correlation with OCT4." (PMID 38233795, 2024). "UTP11 knockdown suppressed the tumor growth of HCC in vivo experiment and extended the mice survival time." (PMID 38233795, 2024). "The results pointed out that the expression of UTP11 was linked to RNA and DNA stemness scores, which implied that with higher expression levels of UTP11, the tumor stemness was stronger." (PMID 38233795, 2024). "In conclusion, UTP11 knockdown suppressed the tumor growth of HCC and extended the mice survival time." (PMID 38233795, 2024). "We first used xenograft model to detect the effect of UTP11 knockdown on subcutaneous tumor growth." (PMID 38233795, 2024). "The tumor weight and size were also decreased in response to UTP11 depletion." (PMID 37087976, 2023). "Our study showed that UTP11 may mediate tumor stem cells in HCC by stabilizing the mRNA of Oct4." (PMID 38233795, 2024).
neurodegenerative disease (1 paper, 2023). A disorder of the central nervous system characterized by gradual and progressive loss of neural tissue and neurologic function.
UTP11 also shares sentences with these, for which no sentence is quoted: atherosclerosis (1 paper); Intellectual disability (1); microcephaly (1); microtia (1); migraine (1); neuroblastoma (1); Pectus carinatum (1).